SH3BGRL2 (SH3 domain binding glutamate rich protein like 2)
Tractability: PROTAC: ubiquitination databases record sites on it; its protein half-life has been measured.
Gene: Protein-coding gene on chromosome 6 (79,537,185 to 79,703,655, forward strand). Ensembl gene ENSG00000198478.
Subcellular location: Nucleus
Subcellular location (Human Protein Atlas): Nucleoplasm
Gene Ontology:
Molecular function: protein-macromolecule adaptor activity
Cellular component: nucleoplasm; nucleus
Genetic constraint (gnomAD): Loss-of-function variants: 15 observed, 10.53 expected, observed/expected ratio (o/e) 1.42, 90% interval 0.94 to 1.9. The upper end of that interval is the gene's LOEUF score, 1.9, which puts it in group 6 of 6, group 1 being the genes least tolerant of losing a copy. Missense variants: 117 observed, 101.88 expected, observed/expected ratio (o/e) 1.15, 90% interval 0.99 to 1.34. Synonymous variants: 43 observed, 38.53 expected, observed/expected ratio (o/e) 1.12, 90% interval 0.87 to 1.44.
Homologues: Orthologues: chimpanzee SH3BGRL2 (100% identical), macaque SH3BGRL2 (100% identical), dog SH3BGRL2 (94% identical), mouse Sh3bgrl2 (93% identical), rat Sh3bgrl2 (91% identical), rabbit SH3BGRL2 (88% identical), pig SH3BGRL2 (84% identical), guinea pig SH3BGRL2 (76% identical), tropical clawed frog sh3bgrl2 (71% identical), zebrafish sh3bgrl2 (67% identical). Paralogues in human: SH3BGR (64% identical), SH3BGRL (64% identical), SH3BGRL3 (37% identical).
Diseases named in the same sentence as SH3BGRL2 in open-access papers:
SH3BGRL2 is named in the same sentence as 18 diseases in open-access papers, as found by Europe PMC text mining. Sharing a sentence is not in itself a finding about the gene and the disease. The quoted sentences say what the papers report.
breast carcinoma (2 papers, 2021). "Further research found that SH3BGRL2 promotes breast cancer cell migration and invasion by inhibiting the expression of SPTAN1 and SPTBN1." (PMID 33390831, 2021). "In terms of functional analysis, the gene SH3BGRL2 has been hypothesized to be a tumor suppressor in renal cell carcinoma and serve a role in the migration and invasion of breast cancer." (PMID 33946483, 2021).
clear cell renal cell carcinoma (2 papers, 2022 to 2023). "This concept finds partial support in previous studies indicating that SH3BGRL2 acts as a tumor suppressor in clear cell renal cell carcinoma." (PMID 37686146, 2023). "SH3BGRL2 is also considered by various studies to play a role as a key tumor suppressor in the occurrence of cancers, such as glioblastoma and clear cell renal cell carcinoma." (PMID 35028969, 2022).
renal cell carcinoma (2 papers, 2021). "As recent literature postulated SH3BGRL2, a homolog of SH3BGR, to affect the Hippo signaling pathway in renal cell carcinoma, we aimed to find whether SH3BGR affects Hippo signaling in neonatal cardiomyocytes." (PMID 34681711, 2021).
breast tumors (1 paper, 2021). "SH3 domain-binding glutamic acid-rich-like protein 2 (SH3BGRL2) has a dual role in breast tumors." (PMID 33390831, 2021).
colon cancer (1 paper, 2026). "Deposited interactomes derived from HCT116 and HKe-3 colon cancer cell lines, as well as HEK293 cells include numerous proteins directly associated with the actin cytoskeleton in the datasets for SH3BGRL and SH3BGRL-2 26–28." (PMID 41565790, 2026).
congestive heart failure (1 paper, 2018). Failure of the heart to pump a sufficient amount of blood to meet the needs of the body tissues, resulting in tissue congestion and edema. "We noted increased SNO modification (–ve RoR value) of three proteins (THBS1, S100A6, abd SH3BGRL2) in ChD patients in this study, as well in congestive heart failure (CHF) patients of idiopathic etiology in a previous study." (PMID 30697201, 2018).
gestational diabetes (1 paper, 2020). Carbohydrate intolerance first diagnosed during pregnancy. "Of note, SH3BGRL2 was identified as a gene that is implicated in type 1 diabetes, type 2 diabetes and gestational diabetes in a transcriptome meta-analysis of peripheral lymphomononuclear cells." (PMID 32894123, 2020).
tumor (11 papers, 2012 to 2024). "Cell growth in vitro and xenograft tumor growth in vivo in BC tumors were inhibited where SH3BGRL2 was downregulated." (PMID 38478326, 2024). "Collectively, we found that the 6q14.3 deletion decreased SH3BGRL2 expression, which downregulated the O‐linked glycan biosynthesis, ultimately weakening the EMT process, inhibiting the tumor cell growth, and resulting in a good prognosis for patients with CCA." (PMID 35716043, 2023). "Given the potential tumor suppressor functionality of SH3BGRL2 in PCa, the dual downregulation observed here presents a plausible hypothesis." (PMID 37686146, 2023). "CDCA7, CELSR3, PACS1, SNTB1, and TBC1D31 showed consistent upregulation in CRC tumor samples and pre-surgical cfRNA, while GFI1B, HPGD, SH3BGRL2, SIAE, PKHD1L1, and TDP2 showed downregulation in CRC tumor samples and pre-surgical cfRNA." (PMID 37091184, 2023). "SH3 domain binding glutamate-rich protein-like 2 (SH3BGRL2) is critical for EMT progression and metastasis in ccRCC, and SH3BGRL2 exerts tumor inhibition through the Hippo pathway." (PMID 36483738, 2022). "We found a large down-regulation of SH3BGRL2 mRNA levels and even though the other two family members, SH3BGRL and SH3BGRL3, were not significantly down-regulated both showed lower expression in tumours (−1.7 and −3.2 fold respectively) indicating that the whole family may be decreased in tumours." (PMID 22530001, 2012).
cancer (2 papers, 2022). A tumor composed of atypical neoplastic, often pleomorphic cells that invade other tissues. "As a result, three genes, SH3BGRL2, TJP3 and TRIM31, were positively correlated with TMPRSS2 and TMPRSS4 for all cancer cell lines and showed distinct differential expression profiles across GI solid tumors." (PMID 35970857, 2022).
SH3BGRL2 also shares sentences with these, for which no sentence is quoted: congenital blindness (1 paper); glioblastoma (1); hyperopia (1); Nystagmus (1); Photophobia (1); retinal dystrophies (1); serous ovarian cancer (1); type 1 diabetes (1); type 2 diabetes (1).